LEMD2 (LEM domain nuclear envelope protein 2)
Description:
Nuclear lamina-associated inner nuclear membrane protein that is involved in nuclear structure organization, maintenance of nuclear envelope (NE) integrity and NE reformation after mitosis. Plays a role as transmembrane adapter for the endosomal sorting complexes required for transport (ESCRT), and is thereby involved in ESCRT-mediated NE reformation. Promotes ESCRT-mediated NE closure by recruiting CHMP7 and downstream ESCRT-III proteins IST1/CHMP8 and CHMP2A to the reforming NE during anaphase. During nuclear reassembly, condenses into a liquid-like coating around microtubule spindles and coassembles with CHMP7 to form a macromolecular O-ring seal at the confluence between membranes, chromatin, and the spindle to facilitate early nuclear sealing. Plays a role in the organization of heterochromatin associated with the NE and in the maintenance of NE organization under mechanical stress (By similarity). Required for embryonic development and involved in regulation of several signaling pathways such as MAPK and AKT (By similarity). Required for myoblast differentiation involving regulation of ERK signaling (By similarity). Essential for cardiac homeostasis and proper heart function (By similarity).
Synonyms: dJ482C21.1; NET25; LEM2; CTRCT42; MARUPS
Tractability: Antibody: UniProt predicts a signal peptide or a membrane-spanning region. PROTAC: ubiquitination databases record sites on it; its protein half-life has been measured.
Gene: Protein-coding gene on chromosome 6 (33,771,202 to 33,789,148, reverse strand). Ensembl gene ENSG00000161904.
Subcellular location: Nucleus inner membrane; Nucleus envelope; Cytoplasm, cytoskeleton, spindle
Subcellular location (Human Protein Atlas): Nuclear membrane
Pathways (Reactome):
Cell Cycle: Depolymerization of the Nuclear Lamina; Initiation of Nuclear Envelope (NE) Reformation; Nuclear Envelope Breakdown; Sealing of the nuclear envelope (NE) by ESCRT-III
Gene Ontology:
Molecular function: protein binding
Biological process: nuclear envelope organization; protein localization to chromatin; skeletal muscle cell differentiation; nuclear membrane organization; heart formation; negative regulation of phosphatidylinositol 3-kinase/protein kinase B signal transduction; neurogenesis
Cellular component: chromatin; endoplasmic reticulum; membrane; nuclear envelope; nuclear inner membrane; nuclear membrane; spindle
Genetic constraint (gnomAD): Loss-of-function variants: 32 observed, 43.93 expected, observed/expected ratio (o/e) 0.73, 90% interval 0.55 to 0.98. The synonymous counts are far from expectation, so gnomAD's model fits this gene poorly and the ratio says little. Missense variants: 626 observed, 549.38 expected, observed/expected ratio (o/e) 1.14, 90% interval 1.07 to 1.22. Synonymous variants: 298 observed, 219.08 expected, observed/expected ratio (o/e) 1.36, 90% interval 1.24 to 1.5.
Homologues: Orthologues: chimpanzee LEMD2 (99% identical), macaque LEMD2 (99% identical), dog LEMD2 (90% identical), pig LEMD2 (89% identical), rat Lemd2 (85% identical), guinea pig LEMD2 (85% identical), mouse Lemd2 (85% identical), Caenorhabditis elegans lem-2 (18% identical), Drosophila melanogaster MAN1 (17% identical). Paralogues in human: LEMD3 (32% identical), ANKLE1 (11% identical).
Diseases named in the same sentence as LEMD2 in open-access papers:
LEMD2 is named in the same sentence as 37 diseases in open-access papers, as found by Europe PMC text mining. Sharing a sentence is not in itself a finding about the gene and the disease. The quoted sentences say what the papers report.
cardiomyopathy (5 papers, 2020 to 2025). A disease of the heart muscle or myocardium proper. "To further understand the pathogenic mechanisms of LEMD2-associated cardiomyopathy, we performed Gene Set Enrichment Analysis (GSEA) on cardiac genes differentially expressed (DE) between WT and KI/KI mice." (PMID 36377660, 2022). "We conclude that a threshold level of LEMD2 is required for normal cardiac function and that its loss leads to cardiomyopathy." (PMID 36377660, 2022). "In this regard, the KI/KI mice represent a valuable tool for studying LEMD2-associated cardiomyopathy and can be utilized to unravel the molecular mechanisms of this condition and to provide a preclinical model for testing potential therapies." (PMID 36377660, 2022). "Regarding the pathogenic basis of Lemd2-associated cardiomyopathy, LEMD2 is located in the INM and has been shown to interact with both lamin A and BAF, two important chromatin regulators." (PMID 36377660, 2022). "To investigate the molecular mechanisms underlying cardiomyopathy caused by the LEMD2 c.T38>G mutation in humans, we generated mice carrying the same mutation, using CRISPR-Cas9 technology." (PMID 36377660, 2022). "Our findings highlight the important role of LEMD2 in cardiac homeostasis and provide mechanistic insights into the basis of LEMD2-associated cardiomyopathy." (PMID 36377660, 2022). "To gain mechanistic insights into LEMD2-associated cardiomyopathy, we analyzed the global chromatin organization of the heart by electron microscopy." (PMID 36377660, 2022). "A mutation in the NEP LEM domain–containing protein 2 (LEMD2) causes severe cardiomyopathy in humans." (PMID 36377660, 2022). "The severity of the LEMD2-associated cardiomyopathy in humans highlights the need for therapeutic approaches aimed at targeting the pathogenic cause of the disease." (PMID 36377660, 2022). "These pathological features indicate that the Lemd2 c.T38>G mutation triggers severe cardiomyopathy in mice." (PMID 36377660, 2022). "Mutations in LEMD2 have also been linked to cardiomyopathy in humans." (PMID 39209536, 2024). "However, this work is the first, to our knowledge, to comprehensively study the effects of LEMD2 loss of function in the heart and the pathogenic mechanisms of LEMD2-associated cardiomyopathy." (PMID 36377660, 2022). "Lemd2 cardiac deficiency leads to cardiomyopathy and premature death in mice." (PMID 36377660, 2022). "There are LEMD2 mouse and human models that include an arrhythmogenic cardiomyopathy phenotype." (PMID 38969939, 2024). "There are currently no available treatments for individuals with cardiomyopathy due to LEMD2 mutations." (PMID 36377660, 2022).
progeria (5 papers, 2020 to 2024). "Our findings contribute to a deeper understanding of the clinical and molecular implications of LEMD2‐associated progeroid syndrome, highlighting a distinct impact on metabolic functions." (PMID 38757373, 2024). "Our study broadens the understanding of LEMD2‐associated progeroid syndrome by detailing its phenotypic and molecular characteristics in the first female and fourth reported case, highlighting a distinct impact on metabolic functions." (PMID 38757373, 2024). "This study delves into LEM domain nuclear envelope protein 2 (LEMD2)‐associated progeroid syndrome, elucidating its phenotypic and molecular aspects in the first female and fourth reported case." (PMID 38757373, 2024). "Patients with a defect in LEM domain nuclear envelope protein 2 (LEMD2) leading to LEMD2‐associated progeroid syndrome are exceedingly scarce in number, yet they exhibit shared clinical features including skeletal abnormalities and a prematurely‐aged appearance." (PMID 38757373, 2024). "These three progeria-associated NE proteins, LaA, BAF, and LEMD2, are all involved in nuclear structure and organization and have been implicated in both post-mitotic NE reformation and in repair of nuclear ruptures." (PMID 35269487, 2022). "Our analysis of Lmnahet mice cardiac tissue detected a nuclear protein, Lemd2, as significantly upregulated in progeria mice." (PMID 36201626, 2022). "Further work will be required to establish the role of Lemd2 upregulation in progeria pathogenesis." (PMID 36201626, 2022). "Mutations in emerin lead to Emery–Dreifuss muscular dystrophy, MAN1 mutations cause disorders affecting osteogenesis via deregulated BMP signaling, and LEM2 has been linked to Hutterite-type cataracts, arrhythmic cardiomyopathy and LEMD2-associated nuclear envelopathy with progeria-like phenotype." (PMID 32085595, 2020).
muscular dystrophies (4 papers, 2013 to 2026). "Consistent with that finding, there was no overt muscular dystrophy phenotype in skeletal muscle of Lemd2+/Gt mice." (PMID 25790465, 2015).
breast carcinoma (2 papers, 2020 to 2024). "Given the Lem-D transcripts, Ankle2, TMPO, Emerin, and Lemd2, were overexpressed in breast cancer patient samples and overexpression largely associated with poorer patient outcomes, we next investigated whether the Lem-D proteins were similarly overexpressed in TNBC cell lines." (PMID 38720803, 2024). "There is evidence to suggest that Ankle2, TMPO, Emerin, and Lemd2 expressions are correlated with breast cancer patient outcomes, but larger patient sample numbers are required to confirm this." (PMID 38720803, 2024). "While our study is the first to investigate Lemd2 expression in breast cancer, a previous study has shown Lemd2 overexpression in prostate adenocarcinoma models." (PMID 38720803, 2024). "GENT2, TCGA, and KM plotter were utilized to investigate the expression and prognostic implications of several Lem-D proteins: Ankle2, TMPO, Emerin, and Lemd2 in publicly available breast cancer patient data." (PMID 38720803, 2024). "Unlike the other Lem-D proteins investigation, Lemd2 expression was shown to positively correlate with OS in breast cancer patients." (PMID 38720803, 2024).
breast tumor (2 papers, 2016 to 2024). "Ankle2, TMPO, Emerin, and Lemd2 were significantly overexpressed in breast tumor samples, in comparison to adjacent normal tissue." (PMID 38720803, 2024).
laminopathies (2 papers, 2016 to 2022). "Interestingly, Lemd2 has been shown to biochemically interact with Lmna A and Lemd2 mutations have been associated with the development of other laminopathies." (PMID 36201626, 2022).
cataract (1 paper, 2016). Partial or complete opacity of the crystalline lens of one or both eyes that decreases visual acuity and eventually results in blindness. "While the LEMD2 variant cosegregated with cataracts in 84 family members (including 17 affected individuals), the MUC21 variant did not." (PMID 26788539, 2016). "Using combined genetic and genomic approaches, we mapped cataracts to a small portion of chromosome 6 and propose that they result from a homozygous missense mutation in LEMD2." (PMID 26788539, 2016). "The candidate variants were genotyped in 84 family members, including 17 with cataracts; only the variant in LEMD2 cosegregated with cataracts (LOD = 9.62)." (PMID 26788539, 2016). "LEMD2 c.T38G cosegregated perfectly with the cataract phenotype in a total of 84 individuals including 17 of 17 individuals with cataracts (LOD = 9.62)." (PMID 26788539, 2016). "While the LEMD2 variant cosegregated perfectly with cataracts, the MUC21 variant did not." (PMID 26788539, 2016).
conduction disorders (1 paper, 2024). "Recent studies in mice with a mutation in the nuclear envelope protein LEMD2 (p.L13R) generate dilated cardiomyopathy with a high burden of MVA and conduction disorders." (PMID 38337354, 2024).
Emery-Dreifuss muscular dystrophy (1 paper, 2014). Emery-Dreifuss muscular dystrophy (EDMD) is characterized by muscular weakness and atrophy, with early joint contractures and cardiomyopathy. "Several studies on Emery-Dreifuss muscular dystrophy patients and model organisms support the role of emerin and LEMD2 in muscle integrity, but their potential role in neurons had not been explored." (PMID 24490688, 2014).
lung carcinoma (1 paper, 2022). "For lung cancer, we found three cancer driver genes (HLA-A, CASP8 and LEMD2) and two CGC genes (HLA-A and CASP8) among the unreported genes, and one cancer driver gene (HLA-B) and one CGC gene (FGFR1OP) among the previously reported genes." (PMID 36402776, 2022).
muscle disorders (1 paper, 2015). "In light of these findings and the effects of other LEM domain protein deficiencies in C. elegans and Drosophila, LEMD2 should be considered as a candidate disease gene in humans with muscle disorders." (PMID 25790465, 2015).
prostate tumor (1 paper, 2022). "We also further validated the mRNA and protein expression levels of ANKLE1, EMD, and LEMD2 in human prostate tumor specimens by qPCR, WB, and IHC." (PMID 35650630, 2022). "In addition, we also further validated the mRNA and protein expression levels of ANKLE1, EMD, and LEMD2 in human prostate tumor specimens by qPCR, WB, and IHC." (PMID 35650630, 2022). "Furthermore, we also validated the mRNA and protein expression levels of ANKLE1, EMD, and LEMD2 in human prostate tumor specimens by qPCR, WB, and IHC." (PMID 35650630, 2022).
schizophrenia (1 paper, 2021). A major psychotic disorder characterized by abnormalities in the perception or expression of reality. "Our data reveal a contribution of LEMD2‐regulated genes to human cognitive function and risk of schizophrenia and uncover a previously unexpected overlap of the human phenotypes that converge on gene sets controlled by SATB2 and LEMD2 in pyramidal neuron." (PMID 33319920, 2021).
synucleinopathy (1 paper, 2025). A neurodegenerative disease that is characterized by the abnormal accumulation of aggregates of alpha-synuclein protein in neurons, nerve fibers or glial cells. "Western blots were performed on synucleinopathy and control Neuro 2a cells reveals differential expression of LEMD2 and the ESCRT-III component CHMP7." (PMID 40654851, 2025).
thyroid carcinomas (1 paper, 2020). "In TC, among those over-expressed in males, we found PPARG, previously reported in thyroid carcinomas, ERCC5, MYH11, LEMD2, ZNF133, and IDH1, the latter found to be mutated in thyroid carcinomas." (PMID 32849808, 2020).
Ventricular arrhythmia (1 paper, 2024). "For instance, patients carrying a homozygous mutation (c.38T>G, p.L13R) in the LEMD2 gene develop ventricular arrhythmia and fibrosis." (PMID 39209536, 2024).
cancer (5 papers, 2020 to 2025). A tumor composed of atypical neoplastic, often pleomorphic cells that invade other tissues. "Together these data argue that LRRC59, LEMD2, and CHMP7 together control repair of MN and accumulation of DNA damage in ruptured MN, a major pathophysiological event associated with cancer progression." (PMID 41387506, 2025). "The Lem-D proteins, including Ankle2, Lemd2, TMPO, and Emerin, have been shown to be associated with many of the hallmarks of cancer." (PMID 38720803, 2024).
tumor (4 papers, 2016 to 2024). "Therefore, given abnormal nuclear morphology and uncontrollable proliferation are pre-existing hall marks of tumor cells, it is conceivable that these collectively result in NE ruptures which are unable to be repaired in Lemd2-deficient cells." (PMID 38720803, 2024). "Taken together, all of these results strongly implicated that ANKLE1, EMD, and LEMD2 could serve as major tumor immune infiltration regulators in PRAD." (PMID 35650630, 2022). "This suggests some level of tumor specificity, as the anti-proliferative effect of Lemd2 depletion in TNBC cells was twofold to 2.5-fold higher than observed in MCF10A cells." (PMID 38720803, 2024). "Our data demonstrate that siRNA-mediated depletion of Ankle2, Emerin, and Lemd2 inhibits cell proliferation in a largely tumor-specific manner in TNBC cells." (PMID 38720803, 2024). "Among all LEMs, only the expressions of ANKLE1, EMD, and LEMD2 were correlated with advanced tumor stage and survival prognosis in PRAD." (PMID 35650630, 2022). "Therefore, potential change in the activity of these pathways should also be investigated to further elucidate Lemd2’s role in tumor cell growth." (PMID 38720803, 2024). "While the exact tumor inhibiting mechanism is yet to be established, Lemd2’s role in inducing aberrant nuclear morphology and inhibiting the growth of TNBC could be attributed to Lemd2’s role in NE rupture repair." (PMID 38720803, 2024). "This study further found a new mechanism that ANKLE1, EMD, and LEMD2 expressions may affect the prognosis of PRAD through tumor immune infiltration." (PMID 35650630, 2022). "In addition, we examined the prognostic value of ANKLE1, EMD, and LEMD2 levels and tumor-infiltrating resting NK cells in PRAD, using the Cox proportional hazard model by TIMER." (PMID 35650630, 2022). "Furthermore, we used TISIDB, TIMER, and UCSC Xena databases to investigate the correlation between ANKLE1, EMD, and LEMD2 expressions and tumor-infiltrated immune cells in the tumor microenvironment." (PMID 35650630, 2022). "Our findings build upon the existing knowledge of the roles of Lem-D proteins in tumor cells and demonstrate the role of several Lem-D proteins: Ankle2, TMPO, Emerin, and Lemd2 in TNBC growth and cell survival." (PMID 38720803, 2024).
psychiatric disorder (2 papers, 2021 to 2023). A disorder characterized by behavioral and/or psychological abnormalities, often accompanied by physical symptoms. "Hence, interactions between SATB2 and the inner nuclear membrane protein LEMD2 influence gene expression programs in pyramidal neurons that are linked to cognitive ability and psychiatric disorder etiology." (PMID 33319920, 2021). "We identified three male-specific genes (ARSA, IGF1R, and SNX19) and two female-specific genes (LEMD2 and PCP4) in psychiatric disorders." (PMID 37794117, 2023).
cardiac disease (1 paper, 2022). "In humans, LEMD2 mutations have also been linked to cardiac disease." (PMID 36377660, 2022). "However, the roles of LEMD2 in the heart and the pathological mechanisms responsible for its association with cardiac disease are unknown." (PMID 36377660, 2022). "This is the first study, to our knowledge, to explore the role of LEMD2, a ubiquitous NEP, in heart disease and cardiac development." (PMID 36377660, 2022).
LEMD2 also shares sentences with these, for which no sentence is quoted: glioma (2 papers); Hutterite-type Cataract (2); neurodevelopmental disorder (2); bone sarcoma (1); brain tumors (1); dilated cardiomyopathy (1); influenza infection (1); lactic acidosis (1); Nestor-Guillermo progeria syndrome (1); obsessive-compulsive disorder (1); oral squamous cell carcinoma (1); pancreatic cancer (1); progressive external ophthalmoplegia (1); prostate adenocarcinoma (1); retinal disease (1); retinitis pigmentosa (1); triple-negative breast carcinoma (1).